VCAM1 (vascular cell adhesion molecule 1)
Diseases named in the same sentence as VCAM1 in open-access papers (continued):
Sharing a sentence is not in itself a finding about the gene and the disease.
type 2 diabetes (48 papers, 2007 to 2025). "VCAM-1 also has appeared as a significant indicator of microvascular complications in type 2 diabetes, which would appear to establish its association with outspreading endothelial activation and dysfunction." (PMID 39830114, 2024). "ICAM-1 and VCAM-1 are relevant to chronic inflammatory processes, with an increased risk for type 2 diabetes (T2DM) and cardiovascular diseases (CVD)." (PMID 32795274, 2020). "Patients diagnosed with type 2 diabetes exhibit notably increased serum concentrations of VCAM1, with a strong correlation between VCAM1 levels and the severity of albuminuria." (PMID 39319258, 2024). "ADM has been shown to induce the expression of VCAM-1 and ICAM-1 on human umbilical vein endothelial cells and was associated with an increase in VCAM-1 and ICAM-1 expression in type 2 diabetes patients." (PMID 36362188, 2022). "Patients with type 2 diabetes present significantly elevated serum levels of VCAM1, and VCAM1 levels correlate well with the extent of albuminuria." (PMID 34506229, 2021). "Another sign of impaired endothelial function is elevated levels of circulating soluble iCAM-1 and vCAM-1 in blood, which is partially reflected in our study: the vCAM-1 level was elevated in obese patients with type 2 diabetes." (PMID 30871567, 2019). "Further, metformin was associated with decreased serum soluble vascular cell-adhesion molecule-1 (sVCAM-1) and soluble ICAM-1 levels in patients with type 2 diabetes during a follow up of 4 years." (PMID 29513760, 2018). "Sulforaphane, a known Nrf2 activator, downregulates the expression of VCAM-1 in aortas of mice fed a high fat diet, a known model of type 2 diabetes." (PMID 28253885, 2017). "The level of vascular cell adhesion protein 1 (VCAM-1) is correlated to albuminuria in type 2 diabetic hypertensive patients." (PMID 25140450, 2014). "Longer-term clinical trials might be required to verify the effect of teneligliptin on the expression of ICAM-1/VCAM-1 in type 2 diabetes patients." (PMID 27184495, 2016). "Vildagliptin treatment inhibited the increase in AGEs, RAGE and oxidative stress marker, 8-hydroxydeoxyguanosine levels of thoracic aorta of obese and type 2 diabetic rats, which were in association with decreased gene expression of MCP-1, VCAM-1 and PAI-1 and suppressed activity of NF-κB." (PMID 25582643, 2015). "The study demonstrated for first time that plasma levels of sRAGE is inversely correlated with plasma levels of VCAM-1 which may suggest a protective role of sRAGE against vascular inflammation in type 2 diabetes." (PMID 23964833, 2013). "In addition, increased serum levels of soluble VCAM-1 have been found in type 2 diabetic patients with microvascular complications, similar to E-selectin, and levels of soluble VCAM-1 are elevated in the vitreous of DR patients as well." (PMID 22132315, 2012). "In subjects with type 2 diabetes, a diet high in AGEs increased inflammatory markers, i.e., C-Reactive protein, TNF-α, VCAM-1 and oxidative stress." (PMID 39518960, 2024). "It has been demonstrated that patients with Type 2 diabetes exhibit an attenuated upregulation of ICAM-1, VCAM-1, and E-selectin after various stimuli such as LPS." (PMID 24750819, 2014). "Consistent with this observational data, we previously found that almonds decreased IL-6 and CRP, and TNF-α in Chinese patients with type 2 diabetes but did not affect ICAM-1 or VCAM-1." (PMID 26080804, 2015). "The increase in postprandial triacylglycerols has been shown to be correlated with the increase in TNFα, IL-6 and vascular cell adhesion molecule 1 (VCAM-1) values, in patients with type 2 diabetes, indicating a deleterious proinflammatory effect of postprandial hyperlipidaemia." (PMID 25725623, 2015). "The present data is consistent with the idea that Type 2 diabetes LDL could increase ADAM17 activity in THP-1 monocytes, and their ability to shed TNF-α and VCAM-1." (PMID 17714581, 2007).
myeloma (46 papers, 1993 to 2025). "The VLA-4 and VCAM-1 axis is also functional in HSCs and inhibiting this axis for therapeutic purposes in myeloma may cause unwelcome side effects; the same is also true for AMD3100." (PMID 26415231, 2015). "This prevents interaction of CXCR4 with CXCL12 which further reduces α4β1 (VLA-4) and VCAM-1 activation, promoting myeloma cell exit from bone marrow." (PMID 40296907, 2025). "VLA-4 on the surface of multiple myeloma binding to the VCAM-1 in BMSCs accelerated the homing of multiple myeloma cells and modified the bone marrow microenvironment." (PMID 38951916, 2024). "For example, the VLA4 (Myeloma)–VCAM1 (MSC)-interface activates NFκB in both myeloma and MSCs, inducing IL6 expression in MSCs." (PMID 38598843, 2024). "The interaction between VLA-4 and vascular cell adhesion molecule-1 (VCAM-1) mediates binding between multiple myeloma cells and BMSCs, contributing to the survival of multiple myeloma cells via the activation of the PI3K/AKT pathway and CAM-DR." (PMID 38560563, 2024). "As EMM is often associated with drug resistance, we tested the levels of VCAM1, HGFA and PEDF in the plasma of patients whose CD138+ myeloma cells had been evaluated by ex vivo drug sensitivity resistance testing (DSRT) (n = 44)." (PMID 37568580, 2023). "M2 macrophages also highly expressed VCAM-1, which is known to interact with myeloma cells through VLA-420." (PMID 36702834, 2023). "The activated form of VLA4 binds with high affinity to the ligands, fibronectin and VCAM-1 expressed on BM stromal cells, increasing myeloma cell adhesion and survival within the BM microenvironment." (PMID 34996933, 2022). "The interaction between VLA4 on myeloma cells and VCAM-1 in the bone microenvironment reduces osteoblastogenesis, increases osteoclastogenesis and promotes myeloma bone disease." (PMID 34996933, 2022). "For example, we have recently employed this platform to conduct successful loss-of-adhesion CRISPR screens for integrin α4β1-mediated adhesion of multiple myeloma cells to VCAM-1 upon stimulation of the chemokine receptor CXCR4 with the chemokine CXCL12." (PMID 35440579, 2022). "Interactions via VLA-4 on myeloma cells and VCAM1 on MSCs were found partially responsible for this effect since antibodies blocking VLA-4 blunted the inhibitory effect on Runx2 activity." (PMID 34067236, 2021). "For example, the integrin α4β1-expressed on myeloma cells has been shown to bind to vascular cell adhesion molecule-1 on MSCs." (PMID 34150666, 2021). "The onset of adipogenesis seems to be partially dependent on cell-to-cell integrin α4 (myeloma cells)-VCAM1 (MSCs) interactions, which leads to the activation of protein kinase C β1 signaling (PKCβ1)." (PMID 34067236, 2021). "Among all dysregulated immune-related mRNAs, AEN, CD320, FABP5, and GPI were risk factors for multiple myeloma, while CXCL12, IGKC, NOD2, VCAM1, and WNT5A were protective factors for multiple myeloma." (PMID 34249967, 2021). "More specifically, VLA-4, which binds to VCAM-1 or fibronectin, and LFA (leucocyte function associated antigen)-1, which binds to ICAM-1, bring myeloma cells in contact with BMSCs, respectively." (PMID 33923357, 2021). "In recent research, it was also proved that sialyltransferase inhibition leads to inhibition of tumor cell interactions with VCAM1, and improves survival in a human multiple myeloma mouse model." (PMID 31956364, 2020). "The adherence of myeloma cells to BMSCs by binding to vascular cell adhesion molecule-1 (VCAM-1) also stimulates the release of many factors that regulate osteoclastogenesis and osteoblastogenesis." (PMID 32937821, 2020). "Blockade of VCAM-1 or VLA-4 also inhibited phagocytosis of live NSO myeloma cells by stimulated macrophages and NIH3T3 transformants expressing integrin αVβ3." (PMID 28733045, 2017). "VLA-4 is another receptor on myeloma cells that upon binding to VCAM-1 on BMSCs, promotes homing to the BM." (PMID 26415231, 2015).
myeloma (continued). "α4β1 integrin expression is also characteristic of advanced primary tumors, and it mediates the interaction of cancer cells with VCAM-1, e.g. myeloma cells with VCAM-1 on bone marrow stroma." (PMID 22623428, 2012). "Myeloma cells attach to osteoclasts directly by numerous adhesion molecules, one example being vascular cell adhesion molecule-1 (VCAM-1), with resultant stimulation of osteoclastogenesis." (PMID 22046568, 2011). "Additionally, the CXCL12/CXCR4 axis can increase the expression of cell-endothelium adhesion molecules in the bone marrow, such as vascular cell adhesion molecule-1 (VCAM1) and integrins α4β1, which further enhances multiple myeloma cells homing to the marrow." (PMID 33123472, 2020). "Additionally, the activation of CX3CR1 on human myeloma RPMI-8226 cells increases their adhesion to fibronectin and vascular cell adhesion molecule-1 (VCAM-1), which is associated with the migration of these cells to bone marrow." (PMID 32466280, 2020). "Indeed, patients with ISS-3 myeloma at diagnosis had higher levels of VCAM-1 compared with ISS-1 and ISS-2." (PMID 27232930, 2016). "Our study provides evidence for the prognostic value of VCAM-1 in myeloma patients, suggesting that VCAM-1 could be a suitable target for the development of anti-myeloma therapies." (PMID 27232930, 2016). "We find that HPSE promotes an invasive phenotype mediated by the very late antigen-4 (VLA-4, or α4β1 integrin) in myeloma cells plated on either fibronectin (FN) or vascular endothelial cell adhesion molecule-1 (VCAM-1), ligands that are prevalent in the bone marrow." (PMID 26926788, 2016). "VCAM-1 is also independently correlated with survival, suggesting an important role in the biology of the disease and supporting its targeting with novel anti-myeloma drugs." (PMID 27232930, 2016). "The interaction between myeloma cells and the bone marrow (BM) microenvironment, through vascular cell adhesion molecule-1 (VCAM-1) and α4β1 integrin, stimulates the production of several proosteoclastogenic factors, including the receptor activator of nuclear factor kappa B (NF-κB) ligand (RANKL)." (PMID 26579531, 2015). "Soluble ICAM-1 and VCAM-1 levels were significantly higher in all the patient groups compared with the controls whereas soluble E-selectin was significantly higher in the ovarian, breast and GI cancer groups and lower in the myeloma group." (PMID 7686390, 1993). "Furthermore, our gene expression analysis has identified a number of cellular adhesion molecules and membrane receptors, including Vcam1 and Axl, that could also play a role in interactions between dormant myeloma cells and cells in the endosteal niche." (PMID 26632274, 2015). "The integrin VLA-4 present on the surface of myeloma cells binds to VCAM-1, vascular cell adhesion molecule-1, and fibronectin, facilitating the proliferation of these tumor cells." (PMID 35663420, 2022). "Treatment with IMiDs decreases the expression of vascular-cell-adhesion molecule 1 (VCAM-1) and intercellular adhesion molecule 1 (ICAM-1), which play key roles in the adhesion of multiple myeloma to the bone marrow compartment." (PMID 34638271, 2021). "The adhesion of myeloma cells is mediated by the adhesion molecule very-late antigen 4 (VLA-4), which binds to the vascular cell adhesion molecule 1 (VCAM-1) expressed by the uncommitted osteoblasts." (PMID 33224935, 2020). "In our study, we evaluated a large number of myeloma patients and found that patients with NDMM had higher levels of VCAM-1 and ICAM-1 compared with MGUS patients and higher VCAM-1 levels compared with SMM patients." (PMID 27232930, 2016). "Once these myeloma cells enter the bone marrow, they adhere to the bone marrow stromal cells through the interaction of CXCR4/stromal derived factor (SDF)-1, VLA-4/VCAM-1, LFA-1/ICAM-1, or others." (PMID 24252328, 2013).
myeloma (continued). "Myeloma cells induce RANKL expression in stromal cells through direct cell-to-cell contact, involving adhesion systems such as very late antigent-4 (VLA4) integrin on myeloma cells and vascular cell adhesion molecule-1 (VCAM1) on stromal cells." (PMID 39595124, 2024). "It is envisioned that in myeloma this mechanism plays a major role in the extravasation of myeloma throughout the bone marrow by engaging VCAM-1 expressed by the vascular endothelium of bone marrow capillaries and VCAM-1 and fibronectin that are richly expressed in the bone marrow stroma." (PMID 34778093, 2021). "MSCs from myeloma patients (MM-MSCs) interrelate with MM cells and change the expression of certain angiogenic and growth factors (such as CD40/40L, VCAM-1, ICAM-1, LFA-3 and HO-1) and several cytokines (IL-6, IL-10 TGFb1, macrophage inflammatory protein-1b (MIP-1b) and IL-7)." (PMID 33923357, 2021). "Sialyltransferase inhibitor may suppress relationships between E-selectin, VCAM1, and MADCAM1, thereby prolonging survival time of multiple myeloma patients." (PMID 34249967, 2021). "Both MM cell and TNFα required the presence of p62 in BMSC for their induction of the protein levels of vascular cell adhesion molecule-1 (VCAM1), which mediates BMSC-MM cell interactions, IL6, a pro-inflammatory and myeloma pro-survival factor, and RANKL, important for osteoclastogenesis." (PMID 30008697, 2018). "Furthermore, high VCAM-1 circulating levels correlated with advanced ISS stage and inferior survival in both the univariate and multivariate analysis in newly-diagnosed myeloma patients." (PMID 27232930, 2016). "Myeloma cell adhesion to BMSCs or extracellular matrix components by expression of adhesion molecules such as Syndecan-1, intercellular adhesion molecule 1 (ICAM-1) or vascular cell adhesion protein 1 (VCAM-1) prevent apoptosis, resulting in cell-adhesion driven drug resistance." (PMID 37744361, 2023). "Transendothelial migration of human myeloma cell lines in vitro and in vivo and primary MM PCs in vitro could be completely blocked using antibodies against VCAM-1, integrin α4 or integrin β1, suggesting a role for integrin α4β1-VCAM-1 interaction in adhesion to BMECs and subsequent extravasation." (PMID 33291672, 2020).
Insulin resistance (42 papers, 2010 to 2025). Increased resistance towards insulin, that is, diminished effectiveness of insulin in reducing blood glucose levels. "While no endothelial-specific biomarkers (e.g., vascular cell adhesion molecule-1 (VCAM-1)) were measured, this trend aligns with known associations between insulin resistance and endothelial impairment." (PMID 40909064, 2025). "Our data showed an increase in active GSK3β in ECs after the insulin resistance, which was associated with a concurrent increase in VCAM1 and ADAM10 and 17 expressions." (PMID 37762417, 2023). "We also observed that in the presence of Wortmannin, a biochemical inhibitor of phosphatidylinositol 3-kinase (a hallmark of insulin resistance), VCAM-1 expression was greater in the presence of TNFα plus insulin as compared to that seen with insulin or TNFα alone." (PMID 22093181, 2011). "NFκB activation further induces the release of pro-inflammatory cytokines such as IL-6, TNFα, ICAM-1, and VCAM-1, which ultimately exacerbates insulin resistance in diabetic patients." (PMID 40369521, 2025). "The activation of GSK3β in ECs after insulin resistance upregulates VCAM1 expression, and VCAM1’s ectodomain is cleaved by the metalloproteases ADAM10 and ADAM17, which also show increased expression in diabetic ECs." (PMID 37762417, 2023). "Here, we have uncovered that insulin resistance leads to the activation of GSK3β in mesenteric artery endothelial cells, which upregulates VCAM1 expression." (PMID 37762417, 2023). "Different studies have demonstrated that miR-126 decreases VCAM-1 expression and can promote insulin resistance by inhibiting IRS-1." (PMID 36139749, 2022). "High levels of CRP are also involved in the production of adhesion molecules, namely, E-selectin, ICAM-1, and VCAM-1, which play a role in vascular endothelial dysfunction, insulin transport reduction, and peripheral insulin resistance." (PMID 31485456, 2019). "The question remains, however, does insulin in the context of insulin resistance/hyperinsulinemia exacerbate or mitigate the existing conditions of TNFα-stimulated VCAM-1 expression?" (PMID 22093181, 2011). "VCAM-1 is one such adhesion molecule that is upregulated in the state of insulin resistance and hyperinsulinemia." (PMID 22093181, 2011). "hyperinsulinemia and insulin resistance appear to augment the inflammatory effects of TNFα on VCAM-1 expression and NFκB translocation, both of which are markers of inflammation in the vasculature." (PMID 22093181, 2011). "Insulin resistance also increases the vasoconstrictor tone by upregulating NF-kB transcriptional activity to induce the expression of endothelin-1 and of pro-inflammatory cell adhesion molecules, such as vascular cell adhesion molecule-1 (VCAM-1)." (PMID 35457157, 2022). "A study found that elevated levels of VCAM-1 in non-obese patients with polycystic ovary syndrome was associated with insulin resistance, independent of the BMI." (PMID 23113882, 2012). "Endothelial insulin resistance leads to increased expression of intracellular adhesion molecule 1 (ICAM-1) and vascular cell adhesion molecule 1 (VCAM-1) due to the downregulation of the insulin receptor–Akt1 pathway." (PMID 40149860, 2025). "In addition, insulin resistance in endothelial cells causes an increased level of prothrombotic factors, proinflammatory markers, and ROS, that lead to an increase in the intracellular levels of adhesion molecule 1 (ICAM-1) and vascular cell adhesion molecule 1 (VCAM-1)." (PMID 30170598, 2018). "Inflammatory factors such as adhesion molecules (ICAM-1 and VCAM-1), CD40 ligands, C-reactive protein (CRP) and myeloperoxidase (MPO) participate in induction of insulin resistance and atherosclerotic disease." (PMID 21247435, 2011). "Since basal Akt activity phosphorylates and deactivates GSK3β, we hypothesized that insulin resistance likely led to an activation of GSK3β, which induced ADAM10/17 and VCAM1 expression." (PMID 37762417, 2023).
Insulin resistance (continued). "Insulin resistance also contributes to elevated levels of proinflammatory markers and ROS, leading to increased intracellular levels of adhesion molecule-1 (ICAM-1) and VCAM-1 in endothelial cells." (PMID 37189834, 2023). "At the end of the study, FFR had developed insulin resistance, aortic NADPH oxidase activity, increased SBP, plasma TBARS and vascular cell adhesion molecule-1 (VCAM-1) expression in mesenteric arteries, and a decrease in heart endothelial nitric oxide synthase (eNOS)." (PMID 21876795, 2011). "Furthermore, in the women with insulin resistance, intake of MOJ for 4 weeks reduced the plasma VCAM-1 levels (554.99 ± 15.63 to 545.31 ± 14.65 ng·mL−1, p = 0.039) but the plasma levels of ICAM-1, C-reactive protein, TNF-α, IL-6, and IL-10 were not significantly altered." (PMID 37469434, 2023). "We found that plasma levels of visfatin, vaspin, VCAM-1, ICAM-1, E-selectin, and Ang-2 were similar in the insulin resistance and non-insulin resistance groups." (PMID 31771561, 2019).